IL6 (interleukin 6)
Diseases named in the same sentence as IL6 in open-access papers (continued):
Sharing a sentence is not in itself a finding about the gene and the disease.
glioblastoma (continued). "One study found that knocking down APOE in glioblastoma cells altered cytokine secretion (increased IL-6/IL-12/TNF-α and decreased CCL5/TGF-β) and reduced the proportion of M2 macrophages in a co-culture system." (PMID 40745073, 2026). "IL6 is known to promote tumor proliferation and survival in glioblastoma through the JAK/STAT3 signaling pathway." (PMID 41282050, 2025). "To translate these findings to a combination treatment strategy for recurrent glioblastoma patients, we show that IL-6 blockade plus ICI durably sensitizes mouse glioblastoma to high-dose radiotherapy." (PMID 40161763, 2025). "Markers of innate immunity including CD68, S100A9, HLADR, NLPR3, interleukin (IL) 1β, IL-6, TNFα and NF-κB were significantly increased in human derived glioblastoma samples compared to healthy control brain." (PMID 41034696, 2025). "In human U251 and TG1 glioblastoma cells, rutin and quercetin reduced the expression of mRNA for IL-6 and IL-10 while increasing TNF expression." (PMID 41009025, 2025). "Subsequent over-expression of TIM-3 in glioblastoma cell lines led to an NFκB/interleukin-6 (IL-6)-dependent enhancement of proliferation, migration, and invasion in vitro, and significant tumor growth and reduced mouse survival in vivo." (PMID 40072074, 2025). "We also show that the SB28 mouse glioblastoma model closely recapitulates the TIME of human glioblastomas and that multiple immune-activating gene therapies decrease intratumoral IL-6 levels in SB28 tumors." (PMID 40161763, 2025). "Tumor-derived exosomes can transport pro-angiogenic cytokines within glioblastoma, including VEGF, FGF, TIMP-1/2, IL-8, and IL-6, thereby instigating both angiogenesis and glioblastoma cell proliferation." (PMID 40821116, 2025). "Specifically, HSPCs were identified within the glioblastoma tumor microenvironment, further promoting glioblastoma cell proliferation and secreting pro-metastatic factors such as IL-6 and CCL2, alongside increased PDL1 expression by cancer cells." (PMID 40822347, 2025). "Combined IL-6 and PD-1 blockade reprograms the glioblastoma immune microenvironment and improves survival in preclinical models." (PMID 40161763, 2025). "IL-6 is a factor involved in glioblastoma malignancy, promoting processes such as renewal, invasion, and angiogenesis." (PMID 40497976, 2025). "Combined IL-6 and PD-1 blockade synergizes with radiotherapy to reprogram the glioblastoma TIME and significantly improve survival in preclinical models." (PMID 40161763, 2025). "Astrocytes then become activated and start secreting elevated amounts of chemokines (e.g. IL-6), enhancing glioblastoma cell invasion and tissue infiltration by increased production MMPs, especially MMP-2 and MMP-9." (PMID 41208963, 2025). "For example, circulating IL-6 levels are elevated in cancer patients, including those with glioblastoma, in whom it appears to promote autophagy and chemotherapy resistance in malignant glial cells." (PMID 40069869, 2025). "TMZ-induced senescent glioblastoma cells are also characterized by proinflammatory cytokine production, including the cytokines IL-1, IL-6, IL-8 and TNF-α and thus display the senescence-associated secretory phenotype (SASP)." (PMID 41350483, 2025). "RBPJ, a crucial TF in Notch signaling was found to promote glioblastoma progression through the IL-6/STAT3 axis in vitro." (PMID 40660393, 2025). "In glioblastoma, IL-6 is pivotal for immunosuppression, with elevated expression in tumor tissues correlating with disease progression and higher malignancy grades." (PMID 40443668, 2025). "Immune stimulatory gene therapy suppresses IL-6 tumor levels in preclinical murine models of glioblastoma." (PMID 40161763, 2025). "Glioblastoma cell-derived EVs upregulated the expression of the pro-tumor genes in microglia cells, including the CXCL1/10, CCL2/CCL5, and IL-6, and downregulated immune response-associated genes, such as IL-16, IL-23, and IL-2740." (PMID 39781357, 2025).
glioblastoma (continued). "Intratumor delivery of IL-6 blockade was unable to reprogram the glioblastoma TIME or prolonging survival, even when combined with PD-1 blockade, suggesting that blockade of IL-6 from sources outside the TIME is required for treatment efficacy." (PMID 40161763, 2025). "Efficient STAT3 gene editing downregulated VEGF, IL‐6, and IL‐10 to reprogram disordered vasculature and the immunosuppressive microenvironment for glioblastoma therapy." (PMID 38923275, 2024). "Another study in 15 recurrent glioblastoma patients showed that TNFα, IFNγ and IL-6 were increased in cerebrospinal fluid 72 h after treatment with the adenovirus Delta24-RGD." (PMID 39196415, 2024). "The downregulation of downstream vascular endothelial growth factor (VEGF) reprograms vasculature normalization to improve immune infiltration, collaborating with interleukin‐6 (IL‐6) and interleukin‐10 (IL‐10) reduction to develop anti‐glioblastoma responses." (PMID 38923275, 2024). "Upon desialylation of the glioblastoma cells, this induction of CD163 was hampered, and furthermore, the monocytes were now able to secrete higher amounts of IL-6 and TNFα compared to fully sialylated glioblastoma cells." (PMID 39065651, 2024). "For example, endothelial-derived IL6 can induce alternative macrophage polarization in glioblastoma." (PMID 38532508, 2024). "Studies have demonstrated that STAT3 activation, induced by IL-6 signaling, specifically promotes cell invasion and migration in U251 and T98G glioblastoma cells." (PMID 38275876, 2024). "The Glioblastoma multiforme (GBM)‐derived IL‐6 promotes tumor growth by upregulating PD‐L1 expression in myeloid cells." (PMID 37452653, 2024). "On the other hand, AT-MSCs can have an inhibitory effect against the 8MGBA glioblastoma cell line due to the synergistic action of the soluble factors it releases, which include IL-6, IFN-γ, and G-CSF." (PMID 38607056, 2024). "Downstream VEGF downregulation reprograms vasculature normalization to improve immune infiltration, collaborating with IL‐6 and IL‐10 reduction to develop anti‐glioblastoma responses." (PMID 38923275, 2024). "In vitro, OV-Cmab-hCCL5-infected human glioblastoma cells supernatant increased the phagocytic activity and IL-1, IL-6, IL-12, and NOS2 expression of human monocyte-derived macrophages." (PMID 39196415, 2024). "In this perspectives article, we present evidence for a potential role of primary cilia as master regulators of glioblastoma-mediated immunosuppression through the regulation of IL-6." (PMID 38188300, 2023). "Concomitantly, anti-IL-6 therapy improved overall survival by 30% in a GL261 murine glioblastoma model." (PMID 38188300, 2023). "In the course of glioblastoma, IL-6 is also involved, in fact, it possesses an anti-inflammatory action and influences cell invasion and migration." (PMID 37759505, 2023). "Glioblastoma tumors can produce IL-6 and drive myeloid immunosuppression by inducing PD-L1 expression on MDSCs." (PMID 38239396, 2023). "In glioblastoma, IL-6 secreted by endothelial cells induces macrophage M2-like polarisation by increasing ARG1 expression." (PMID 37462801, 2023). "Nonetheless, anti-IL-6 monotherapy only showed modest efficacy in in vivo preclinical glioblastoma models." (PMID 38188300, 2023). "It has been documented that SH2B3 contributes to glioblastoma progression by transducing IL-6/gp130/STAT3 signaling." (PMID 37426414, 2023). "It is evident that IL-6 is crucial for coordinating the M2 macrophage response in the glioblastoma microcompartment." (PMID 38188300, 2023). "Glioblastoma secretion of IL-6 increased PD-L1 expression on peripheral myeloid cells, promoting T cell anergy." (PMID 38188300, 2023). "Specifically, results of TCGA dataset analysis suggest poor prognosis for IL6 overexpressing low grade gliomas and glioblastomas." (PMID 37006265, 2023). "Glioblastoma and pancreatic adenocarcinoma are reliant on EVs and IL-6 for immune modulation and cellular proliferation." (PMID 38188300, 2023).
glioblastoma (continued). "IL-6 is a cytokine that is known to trigger JAK-STAT3 signaling in glioblastoma, gliomagenesis, MGMT methylation, and is correlated with tumor grade and overall patient survival." (PMID 37752585, 2023). "It is possible that primary cilia, as the principal organelle in microenvironment sensing and communication, is involved in regulation of both IL-6 and glioblastoma EVs." (PMID 38188300, 2023). "PGK1 T243 phosphorylation induced by interleukin-6 (IL-6) secreted from polarized M2 macrophages induces tumor cell glycolysis and tumorigenesis in human glioblastoma multiforme." (PMID 37226192, 2023). "Second, the determination of samples from patients indicated that the width of the glioblastoma (GBM) was directly associated with fibrinogen and IL-6 levels in diabetic glomerulopathy." (PMID 36776877, 2023). "The pleiotropic cytokine, IL-6, is implicated in the recruitment of monocytes and lymphocytes, and IL-6 mRNA is abundantly present in all glioblastoma lines investigated." (PMID 36430641, 2022). "IL-6 secreted by in situ macrophages regulated the direction of a PGK1-catalyzed reaction by increasing PDPK1-dependent PGK1 phosphorylation in glioblastoma cells, promoting glycolysis and proliferation of tumor cells." (PMID 35600367, 2022). "Brd4 inhibition abrogated an the constitutively active mutant form of the EGFR receptor (EGFRvIII)-induced transcription expression of BIRC5 and eliminated IL-6-mediated therapy resistance in glioblastoma." (PMID 36539410, 2022). "Amplification of IL-6 gene directly correlates with glioblastoma aggressiveness leading to decreased patient survival." (PMID 36678688, 2022). "The application of ionizing radiation to human glioblastoma cell line promoted an increase in IL-6 and IL-8 secretion by these cells." (PMID 36675979, 2022). "The hypoxic glioblastoma cells initiate autophagy with the assistance of IL-6 to support tumor cell growth in a nutrient-deprived microenvironment." (PMID 35954362, 2022). "Brd4 has been shown to associate with NF-κB on the promoter of BIRC5 (gene for Survivin) to facilitate mRNA expression of Survivin in glioblastoma cells with IL-6 stimulation." (PMID 36539410, 2022). "The authors also demonstrated the immunomodulatory effects of the treatment of human U251 and TG1 glioblastoma cells with both flavoinds, negatively modulating the expression of mRNA for IL-6 and IL-10 and positively the expression of mRNA for TNF." (PMID 35057010, 2022). "Glioblastoma releases extracellular vesicles (EVs), carrying molecules such as proteins and microRNAs (miRNAs), vascular growth factors, and IL-6,8, which play a role in inducing BBB breakdown." (PMID 35053392, 2022). "Studies have now demonstrated that myeloid PD-L1 expression is induced by glioblastoma cell IL-6 cytokine secretion acting through STAT3." (PMID 36430641, 2022). "A potential role for quercetin in the prevention and treatment of glioblastoma has been demonstrated as a suppressor of the STAT3 activation signaling pathway stimulated by IL-6." (PMID 35883021, 2022). "IL-6 also sustains tumour progression by acting directly on glioblastoma cells to induce anti-apoptotic pathways and promote invasion." (PMID 33803414, 2021). "The synergistic effect of cytokines TNF-α and IL-6 ascertained the belligerent nature of glioblastoma through activation of the NF-κB and STAT3 pathways." (PMID 34439380, 2021). "This peculiar aspect, outlining dual IL-6 functionality in glioblastoma, deserves further investigation." (PMID 34707200, 2021). "A similar trend was observed for IL-6, whose levels increased after 7 days in all primary glioblastoma samples." (PMID 34707200, 2021). "Glioblastoma-derived IL6 is required for up-regulation of myeloid PD-L1 in glioblastoma through a STAT3-dependent mechanism." (PMID 32403421, 2020). "Our group previously showed that CSF of post-herpetic neuralgia (PHN) chronic pain patients induced elevated IL-6 release from human glioblastoma T98G cells." (PMID 32213162, 2020).
glioblastoma (continued). "Studies revealed that IL-6 can contribute to the proliferative and migratory abilities of glioblastoma." (PMID 32194542, 2020). "Recently, microdialysis has been used to measure some IL expressions in glioblastoma and adjacent brain tissue, showing that there was a positive correlation between baseline IL-8 and IL-6 microdialysis levels in tumor tissue and survival." (PMID 32469935, 2020). "Targeting IL-6 signalling has also been shown to suppress survival of glioma stem cells isolated from human glioblastoma xenografts (D456MG, D54MG) or from fresh human surgical specimens and tumour growth." (PMID 32779712, 2020). "In this regard, in glioblastoma cells undergoing hypoxia, stress stimuli, autophagy was activated, and the expression of IL-6 resulted upregulated." (PMID 33424586, 2020). "A correlation between IL-6 gene expression and shortened survival in glioblastoma patients has been demonstrated." (PMID 32878114, 2020). "The involvement of IL-6 in autophagy and tumor progression has been revealed by a recent microRNA study in glioblastoma cells, which demonstrated that IL-6 has an ability to induce autophagy through STAT3 and microRNA-155-3p159." (PMID 32015340, 2020). "T98G glioblastoma cell line was previously observed to release higher amounts of interleukin-6 (IL-6) when treated with cerebrospinal fluid (CSF) from patients with another chronic pain condition, post-herpetic neuralgia." (PMID 32213162, 2020). "More recently, interleukin (IL)-6-induced autophagy has been shown in hypoxic glioblastoma cells via the p-STAT3-MIR155-3p-CREBRF pathway." (PMID 31311917, 2019). "A previous study showed that IL-6 induces the mRNA expression of survivin in glioblastoma cells through mTORC2/NF-kB." (PMID 31908585, 2019). "EGFR variant III (EGFRvIII) was found to potentiate IL-1β-induced IL-6 secretion through the p38 MAPK-MK2-HuR pathway in glioblastoma cells." (PMID 31772161, 2019). "Ketamine reduces NFkB activation in A172 human glioblastoma cells exposed to LPS and reduces TNFα and IL6 production by LPS-stimulated RAW 267.4 (transformed mouse macrophage) cells." (PMID 30666211, 2018). "Of note, increased expression of IL-6, IL-6 receptor or activated (phosphorylated) STAT3 correlated with poor survival of glioblastoma patients, and so does loss of the IL-6 negative regulator SOCS3." (PMID 29601503, 2018). "In this study, after LPS incubation with U87 glioblastoma cell, the pro-inflammatory cytokine TNFα, IL1β, and IL6 levels were elevated; the response was reversed by co-incubation of polysaccharide fractions in LPS." (PMID 29530027, 2018). "Several glioblastoma studies have reported elevated levels of IL-6, IL-10 and TGF-β along with higher STAT3 activity." (PMID 28346397, 2017). "In conclusion, limiting IL-6 function seems to be an eminently worthwhile goal in treating glioblastoma." (PMID 28977822, 2017). "Glioblastoma show IL-6 gene amplification and patients with greater degree of amplification have shorter overall survival." (PMID 28977822, 2017). "There is an IL-6 based positive feedback loop in glioblastoma where extracellular IL-6 results in intracellular STAT3 phosphorylation (activation) that in turn upregulates glioblastoma cells’ IL-6 synthesis." (PMID 28977822, 2017). "This is consistent with studies in glioblastoma showing that inhibition of IL-6 or its receptor, IL-6Rα, diminishes STAT3 activation and, in turn, the number of glioblastoma stem cells." (PMID 26880966, 2016). "In contrast, in glioblastoma cells norm-fractionated radiation resulted in the highest extracellular concentration of IL-6." (PMID 28066420, 2016). "IL6 (interleukin 6), an inflammatory autocrine and paracrine cytokine that is overexpressed in glioblastoma, has been reported to be a biomarker for poor prognosis because of its tumor-promoting effects." (PMID 27163161, 2016).
glioblastoma (continued). "Here, we describe a novel tumor-promoting mechanism of IL6, whereby hypoxia-induced IL6 acts as a potent initiator of autophagy in glioblastoma via the phosphorylated (p)-STAT3-MIR155-3p pathway." (PMID 27163161, 2016). "Previously we found that α7-specific antibody stimulated IL-6 production in cultured U373 glioblastoma cells." (PMID 25816313, 2015). "miR-142-3p is a target of Interleukin 6 (IL6) in glioblastoma and it has been proposed that miR-142-3p blocks the expression of IL6, Hmga2 and Sox2 thereby suppressing the stem like properties of glioblastomas." (PMID 26327117, 2015). "As IL-6, IL-8 promotes angiogenesis and invasiveness of glioblastomas, and is an autocrine survival factor." (PMID 26291724, 2015). "Previously we found that α7 nAChR-specific antibody induced pro-inflammatory interleukin-6 production in U373 glioblastoma cells and that such antibodies were present in the blood of humans." (PMID 25816313, 2015). "In T98G and U87 glioblastoma cells, quercetin inhibits the release of IL-6, an important cancer-related cytokine, which in turn activates the pro-oncogene STAT3 signaling pathway." (PMID 26512639, 2015). "In contrast to the expected effects of ACA on cytokine levels, in the present study, an increased expression of IL-6 and IL-1α was observed in glioblastoma cells treated with ACA." (PMID 23833677, 2013). "Recent results from glioblastoma studies also showed that the IL-6/STAT3 pathway is required for proliferation, survival and tumor growth of glioblastoma stem cells." (PMID 24376586, 2013). "IL-6 is widely expressed in many solid cancers including prostate, breast, lung cancer, and glioblastoma." (PMID 22745766, 2012). "Transfection with miR-146a mimic downregulated IL-1ß induced IL-6 and Cox-2 mRNA levels in both U373 glioblastoma cells and human fetal astrocytes in culture." (PMID 23028621, 2012). "Quantitative phosphorylation events focused on signal transducer and activator of transcription 3 (STAT3)/interleukin 6 (IL6)/hypoxia-inducible factor 2α (HIF2α) autocrine loop were also reported regarding glioblastoma stem cells." (PMID 22912867, 2012). "IL-6, whose production is stimulated by hypoxia and elevated in glioblastoma cells, stimulates the activation of the transcription factor STAT3." (PMID 21655185, 2011). "Using an ELISA, we measured the amount of IL-6 secreted by our medulloblastoma and glioblastoma cell lines." (PMID 21526200, 2011). "Goswami used an anti-IL-6 primary antibody to inhibit the proliferation of human glioblastoma multiforme cells, demonstrating that IL-6 has some effect on promoting tumor cell proliferation." (PMID 21345194, 2011). "The persistent activation of STAT3 is in part, also attributable to an autocrine action of IL-6 in the glioblastoma cells." (PMID 20712901, 2010). "Using quantitative PCR methods, we detected amplification and expression of the IL-6 gene in 5 of 5 primary glioblastoma samples and in 4 of 5 glioblastoma cell lines." (PMID 11506489, 2001). "Given the association between IL-6 expression and glioblastoma outcome, we tested whether IL-6 functionally contributes to glioblastoma growth in murine glioblastoma." (PMID 40161763, 2025). "Furthermore, survival was longer in Il-6 knockout mice with orthotopic SB28 glioblastoma relative to wild-type mice." (PMID 40161763, 2025). "IL-6 induced recruitment of gp130 triggers the yes-associated protein 1 (YAP) signaling and neurogenic locus notch homolog protein (NOTCH) signaling to promote glioblastoma growth in the human brain." (PMID 40843259, 2025). "Notably, IL-6 and the IL-6 signaling cascade support glioblastoma tumorigenesis and stemness, and we identified that genes involved in the IL-6 signaling pathway, such as ANXA1, LGALS3, and EGFR, were enriched in ICI non-responders pre-ICI 28–30." (PMID 40161763, 2025).